FADS2 (fatty acid desaturase 2)
Diseases named in the same sentence as FADS2 in open-access papers (continued):
Sharing a sentence is not in itself a finding about the gene and the disease.
acute coronary syndrome (3 papers, 2013 to 2023). Signs and symptoms related to acute ischemia of the myocardium secondary to coronary artery disease. "An alternative/minor allele of FADS1 rs174537 was linked to T2DM in an Iranian population, and FADS1 rs74556 and FADS2 rs174617 have been linked with acute coronary syndromes." (PMID 35736500, 2022). "Associations between FADS1/FADS2 variants and complex conditions such as MetS, T2DM, and cardiovascular disease (e.g., acute coronary syndromes, CAD, and ischemic stroke) have likewise been described." (PMID 35736500, 2022). "The purpose of this study is to analyze the relationship between the polymorphisms of fatty acid desaturase 1 (FADS1), fatty acid desaturase 2 (FADS2), and elongation of very long-chain fatty acids-like 2 (ELOVL2) and acute coronary syndrome (ACS) in Chinese Han population." (PMID 23555103, 2013).
atopic eczema (3 papers, 2010 to 2018). A common chronic pruritic inflammatory skin disease with a strong genetic component. "A previous study in adults found protective associations of carriers of minor alleles of the FADS1 FADS2 gene cluster with allergic rhinitis and atopic eczema." (PMID 20948998, 2010). "This study suggests that lower mRNA-expressions of FADS2 and ELOVL5 are associated with higher risk of atopic eczema in young children." (PMID 24167612, 2013). "Some of lipid metabolic genes discovered in our analysis were also reported as declined genes in patients with psoriatic (ACSBG1, ALOX15B, ELOVL3, FADS1, FADS2, and THRSP) or atopic dermatitis (CYP4F8, ELOVL3, FADS1, FADS2, FAR2, and HAO2)." (PMID 30021930, 2018). "This is the first study to confirm that FADS2 and ELOVL5 mRNA-expression is significantly lower in the peripheral blood of young children with atopic eczema." (PMID 24167612, 2013).
bladder tumour (3 papers, 2021 to 2025). "This study aimed to further investigate the relationship between FADS2 expression and ferroptosis in bladder tumours." (PMID 40682485, 2025). "The results showed that reduced FADS2 expression led to the release of ferrous ions in tumour tissues, thereby enhancing the sensitivity of bladder tumours to ferroptosis." (PMID 40682485, 2025). "Collectively, these results demonstrate that FADS2 knockdown enhances oxidative stress in bladder tumours, promoting ferroptosis." (PMID 40682485, 2025). "The high expression level of FADS2 was positively correlated with worse survival prognosis in bladder tumour samples (p = 0.036)." (PMID 34095228, 2021).
gastric cancer (3 papers, 2018 to 2025). A primary or metastatic malignant neoplasm involving the stomach. "However, we did not identify a significant modifying effect according to FADS1 rs174546 or FADS2 rs174583 genetic variants on the association between n-3 or n-6 PUFAs and the risk of gastric cancer." (PMID 29491470, 2018). "Therefore, we examined whether dietary n-3 and n-6 PUFAs are associated with the risk of gastric cancer and sought to determine whether FADS1 and FADS2 modify the association between PUFAs and the risk of gastric cancer." (PMID 29491470, 2018). "Thus, we examined whether dietary n-3 and n-6 PUFAs are associated with the risk of gastric cancer and further investigated whether fatty acid desaturases 1 and 2 (FADS1 and FADS2) modify this association." (PMID 29491470, 2018). "In addition, we hypothesized that the risk of gastric cancer associated with dietary n-3 and n-6 PUFAs would vary according to FADS1 or FADS2 genetic variants." (PMID 29491470, 2018). "In conclusion, we observed a significant inverse association between dietary DHA and the risk of gastric cancer but found that FADS1 rs174546 and FADS2 rs174583 did not modify the association between dietary n-3 or n-6 PUFAs and gastric cancer risk." (PMID 29491470, 2018).
non-alcoholic fatty liver disease (3 papers, 2019 to 2022). "Non-alcoholic fatty liver disease has been associated with increased mRNA expression of FADS2 in the liver and estimated activity of delta-6 desaturase in serum, encoded by the FADS2 gene." (PMID 30654845, 2019). "Genetic variants of FADS2 may contribute to the pathogenesis of non-alcoholic fatty liver disease by modifying DNA methylation." (PMID 30654845, 2019). "These proteins were mainly involved in fatty acid metabolism (Fasn, Scd1, Fads2, Fdps, Plin2), fatty acid degradation (Ehhadh, Acsl1), PPAR signaling pathway (Fads2, Ehhadh, Acsl1, Fabp1), non-alcoholic fatty liver disease (Ehhadh, Pklr) and AMPK signaling pathway (Fasn, Scd1, Hnf4a)." (PMID 32210812, 2020). "Moreover, many studies showed that expression levels of FADS2 were positively correlated with non-alcoholic fatty liver disease, and down-regulated FADS2 may contribute to the maintaining the activity of delta-6 desaturase to ensure liver digestive function." (PMID 35351103, 2022).
pancreatic cancers (3 papers, 2022 to 2025). "Genetic variations—particularly single-nucleotide polymorphisms (SNPs) in the FADS1 and FADS2 genes—affect PUFA metabolism, linking circulating PUFA levels to the risk of several cancers, including breast, colorectal, prostate, and pancreatic cancers." (PMID 40430008, 2025). "Also, compared to the control group, pretreatment TMG significantly enhanced ZEB1, O-GlcNAcylation, and FADS2 protein expression levels in the subcutaneous pancreatic carcinoma tissues." (PMID 35844792, 2022).
vitiligo (3 papers, 2019 to 2025). Generalized well circumscribed patches of leukoderma that are generally distributed over symmetric body locations and is due to autoimmune destruction of melanocytes. "The SMR analyses and colocalization analyses results suggest that FCRL3, FADS1, and FADS2 are shared genes associated with both vitiligo and RA." (PMID 40468464, 2025). "The eQTL data of FCRL3, FADS1, and FADS2 were analyzed for colocalization with GWAS data for both vitiligo and RA." (PMID 40468464, 2025). "In SMR analyses and colocalization analyses, we identified three shared genes associated with both vitiligo and RA, including: FCRL3, FADS1, and FADS2." (PMID 40468464, 2025). "We found that compared with adjacent normal controls, vitiligo clinical specimens exhibit significant downregulation of fatty acid desaturase 1 (FADS1), a member of the fatty acid desaturase gene family located along with FADS2 at locus 11q12-13.1." (PMID 31866583, 2019).
adrenal adenomas (2 papers, 2023 to 2025). "In addition, FADS2 expression positively correlated with STAR expression in aldosterone- and cortisol-producing adrenocortical adenomas." (PMID 37478183, 2023).
attention deficit-hyperactivity disorder (2 papers, 2016 to 2022). A disorder characterized by a marked pattern of inattention and/or hyperactivity-impulsivity that is inconsistent with developmental level and clearly interferes with functioning in at least two settings (e.g. at home and at school). "The FADS2 gene is associated with brain-related phenotypes, such as intellectual development and attention-deficit hyperactivity disorder (ADHD)." (PMID 35683524, 2022). "An SNP in FADS2 was found to be significantly associated with the occurrence of attention-deficit/hyperactivity disorder, and dietary consumption of essential fatty acids was found to be related to the dopamine pathway in attention-deficit/hyperactivity disorder in patients." (PMID 26742061, 2016).
bladder urothelial carcinoma (2 papers, 2023 to 2025). "Of all three human desaturases, FADS2 and SCD1 are most frequently dysregulated in cancer, with FADS2 overexpression being associated with increased disease progression in uveal melanoma, bladder urothelial carcinoma, clear cell renal carcinoma, and lung and pancreatic adenocarcinomas." (PMID 40403013, 2025). "There was a significant increase in FADS2 mRNA expression in most types of cancer, such as UCEC, COAD, KIRC, BRCA, LUSC, HNSC, LIHC, and bladder urothelial carcinoma (BLCA)." (PMID 36788618, 2023).
cholangiocarcinoma (2 papers, 2023 to 2025). A carcinoma that arises from the intrahepatic biliary tree (intrahepatic cholangiocarcinoma) or from the junction, or adjacent to the junction, of the right and left hepatic ducts (hilar cholangiocarcinoma). "However, FADS2 mRNA expression was markedly reduced in kidney chromophobe (KICH), cholangiocarcinoma (CHOL), prostate adenocarcinoma (PRAD), kidney renal papillary cell carcinoma (KIRP), and pheochromocytoma and paraganglioma (PCPG)." (PMID 36788618, 2023).
depression (2 papers, 2022 to 2025). "Additionally, some depression-associated genes in the South Asian population are linked to diet and metabolism, such as FADS1, FADS2, LPIN3, and SGIP1." (PMID 40075226, 2025).
dermatitis (2 papers, 2022 to 2025). An inflammatory process affecting the skin. "Mice treated with Fads2 siRNA exhibited markedly aggravated IMQ‐induced skin inflammation, as evidenced by increased ear thickness, elevated PASI scores, pronounced epidermal hyperplasia, and enhanced dermal inflammatory cell infiltration." (PMID 40878384, 2025). "FADS2 deficiency impairs docosahexaenoic acid (DHA) biosynthesis, enhances NF‐κB signaling, and promotes neutrophil‐driven skin inflammation." (PMID 40878384, 2025). "Dermatitis also develops after FADS2-targeted disruption in the skin further supporting the significance of FADS2 expression for normal skin function." (PMID 35219001, 2022).
eczema (2 papers, 2010 to 2024). "Of all analyzed indicator coded SNPs of the FADS1 FADS2 gene cluster none showed a statistically significant association with the dichotomous outcome parental reported eczema in the first 2 years of life in both unadjusted and adjusted analyses." (PMID 20948998, 2010). "With data on variants of the FADS1 FADS2 gene cluster, PUFA and information on eczema status within the first 2 years of life for more than 800 children this is a large study despite the potential lack of power to detect small effects regarding eczema." (PMID 20948998, 2010).
hypertriglyceridemia (2 papers, 2021 to 2022). A laboratory test result indicating elevated triglyceride concentration in the blood. "Regarding associations with hypertriglyceridemia, SNPs on the genes of BCL7B, FADS2, and TM6SF2 were found in previous studies." (PMID 36233190, 2022).
ischemic stroke (2 papers, 2022). A stroke disorder caused by obstruction of blood flow to the brain, due to thrombotic (local blood clot formation) or embolic (due to a blood clot or other material traveling from another site) event. "FADS1 (rs174546) and FADS2 (rs174601) were linked to CAD and ischemic stroke." (PMID 35736500, 2022).
kidney cancer (2 papers, 2024 to 2025). Primary or metastatic malignant neoplasm involving the kidney. "Pan‐cancer analysis of the TCGA database demonstrated that FADS2 is overexpressed in various cancers, including bladder, breast, colon, oesophageal and kidney cancers." (PMID 40682485, 2025). "Remarkably, the levels of FADS2 in different lung and kidney cancer cells correlate with sensitization to apoptosis by co-treatment with unsaturated fatty acids." (PMID 38830851, 2024). "The correlation of FADS2 levels with the sensitization to apoptosis of different lung and kidney cancer cell lines by co-treatment with unsaturated fatty acids supports the relevance of our findings." (PMID 38830851, 2024).
Myocardial fibrosis (2 papers, 2019 to 2024). "Pre-treatment LVESVi, non-infarct myocardial fibrosis, infarct size by LGE, and RV size and function were not significantly different between the 3 FADS2 genotypes." (PMID 31532795, 2019).
nutritional deficiency (2 papers, 2020 to 2021). "Compared to GAPDH, nutritional deficiency increased the expression of FADS2 8 times (p = 0.004) and necrotic conditions 5 times (p = 0.004)." (PMID 32392704, 2020). "Furthermore, results of the recent studies suggest that the genes involved in hepatic lipid synthesis (ACACA, FASN, LPL, SCD1, FADS1, and FADS2) were down-regulated over nutritional deficiency." (PMID 35111749, 2021).
osteoporosis (2 papers, 2020 to 2025). A condition of reduced bone mass, with decreased cortical thickness and a decrease in the number and size of the trabeculae of cancellous bone (but normal chemical composition), resulting in increased fracture incidence. "For osteoporosis-related traits, the most strong association signal was observed at the rs174577 of FADS2 gene (MTAG P value = 2.66 × 10−7)." (PMID 32107650, 2020). "MTAG analysis identified several novel candidate genes, such as CTNNA2 (MTAG P value = 2.24 × 10−6) for SCZ and FADS2 (MTAG P value = 2.66 × 10−7) for osteoporosis." (PMID 32107650, 2020).
ovarian tumor (2 papers, 2023 to 2024). "Treatment of ovarian tumor cells with SCD1/FADS2 inhibitors in combination with ferroptosislatin can raise the rate of apoptosis, decrease the rate of cell mobility and tumor metastasis, and increase the sensitivity of ovarian tumor cells to ferroptosislatin." (PMID 39192972, 2024).
uveal melanoma (2 papers, 2023 to 2025). A melanoma derived from melanocytes of the uveal tract. "A higher FADS2 expression has been associated with reduced OS in BLCA, KIRP, LUSC, PCPG, mesothelioma (MESO), thyroid carcinoma (THCA), and uveal melanoma (UVM)." (PMID 36788618, 2023).
adenoma (1 paper, 2023). A neoplasm arising from the epithelium. "In humans, FADS2 expression is elevated in aldosterone-producing adenomas compared to non-active adenomas or nontumorous adrenocortical tissue and correlates with expression of steroidogenic genes." (PMID 37478183, 2023). "We demonstrate that FADS2 expression is higher in aldosterone-producing adenomas compared to nonfunctioning adenomas or nontumorous adrenocortical tissue and correlates with the expression of STAR in aldosterone- and cortisol-producing adenomas." (PMID 37478183, 2023).
adrenal tumors (1 paper, 2023). "Along this line, we investigated the changes in FADS2 expression in human adrenal tumors." (PMID 37478183, 2023).
AIDS (1 paper, 2025). A syndrome resulting from the acquired deficiency of cellular immunity caused by the human immunodeficiency virus (HIV). "Finally, we sought to investigate the role of SCD1 and FADS2 in EBV+ tumor cells using the AIDS-associated immunoblastic lymphoma cell line, IBL-1." (PMID 40403013, 2025). "We found that similar to LCLs, combined SCD1 and FADS2 inhibition arrested growth and hypersensitized EBV+ AIDS immunoblastic lymphoma IBL-1 cells to increased palmitate, pointing towards a unique targetable mechanism in EBV-associated lymphomas." (PMID 40403013, 2025).
Anxiety (1 paper, 2025). Intense feelings of nervousness, tension, or panic often arise in response to interpersonal stresses. "Interestingly, we identified 13 overlapping genes regulated in the overexpression experiment and only three genes regulated in the lbx1a(−/−) mutant line (NPM1, PCLO, and FADS2), which are candidate genes from anxiety GWAS studies." (PMID 41440000, 2025).
colitis (1 paper, 2023). Inflammation of the colon. "FADS2 inhibition also showed beneficial effects possibly related to trained immunity in a colitis mouse model." (PMID 37968313, 2023). "Thus, we set out to explore this possibility by means of FADS2 inhibition in a mouse model of colitis." (PMID 37968313, 2023). "Indeed, we show that FADS2 inhibition decreased both in vitro BCG-increased responsiveness and colitis severity in a murine model." (PMID 37968313, 2023).
colorectal polyp (1 paper, 2024). "We report that the FADS Indel, a functional 22 bp insertion-deletion polymorphism in FADS2 (rs66698963), which is known to direct FADS1-dependent synthesis and availability of the n–6 HUFA AA, stratifies participants in the seAFOod trial that display colorectal polyp prevention by the n–3 HUFA EPA." (PMID 38879016, 2024).
colorectal tumors (1 paper, 2017). "Box plots of colorectal tumor versus normal tissue gene expression profiles for FADS2, COLCA2, COLC1, and CABLES2 (right column)." (PMID 28506205, 2017). "We also observed a strong indication for association between rs1535 with FADS2 expression (p = 1.51 × 10−4) in colorectal tumor tissue; however this association did not meet the significance cut-off of FDR ≤ 0.05 after multiple text correction." (PMID 28506205, 2017). "Our analysis of FADS2 gene expression in colorectal tumor versus normal tissue indicate that FADS2 is upregulated in colorectal tumors compared to normal tissue (p = 5.21 × 10−7), supporting the observation that disruption of FADS2 expression may also have an important role in CRC." (PMID 28506205, 2017). "Box plots of gene expression profiles for FADS2, COLCA2, COLC1, and CABLES2 expression by genotype (cis-eQTL) in colorectal tumor tissue (left column)." (PMID 28506205, 2017).
Conn adenomas (1 paper, 2023). "Increased FADS2 expression in Conn adenomas was associated with enhanced pre-operative aldosterone levels in these patients compared to patients of the two other groups." (PMID 37478183, 2023).
endometriosis (1 paper, 2023). The growth of functional endometrial tissue in anatomic sites outside the uterine body. "FADS-2, a member of fatty acid desaturase, is rarely studied in endometriosis, but both FADS-2 and HMOX1 are involved in ferroptosis, a new programmed cell death characterized by the accumulation of lipid reactive oxygen species (ROS) and dependence of iron." (PMID 38012607, 2023). "We identified HMOX1 and FADS-2 as potential endometriosis molecular treatment targets in the future." (PMID 38012607, 2023).
gallstones (1 paper, 2018). Solid crystalline precipitates in the biliary tract, usually formed in the gallbladder, resulting in the condition of cholelithiasis. "Six of the novel gallstone associated variants, or highly correlated variants (r2 > 0.8), have been reported to associate with blood cholesterol levels (in HNF4A, HNF1A, FUT2, FADS2, MARCH8, and JMJD1C)." (PMID 30504769, 2018).
hepatitis B (1 paper, 2018). "The reduced level of PUFA (n-3, n-6), is possibly due to lower activities of ∆ 5 desaturase and ∆ 6 desaturase enzymes and higher activity of ∆ 9 desaturase in hepatitis B patients that enumerate impair activity of FADS1 and FADS2." (PMID 29506525, 2018).
Hepatitis C (1 paper, 2025). "The non-canonical desaturation of oleate to Mead acid and other highly unsaturated fatty acids, mediated by FADS2, facilitates the ferroptosis pathway, which in turn attenuates Hepatitis C viral replication." (PMID 40535804, 2025).
Hypercholesterolemia (1 paper, 2017). An increased concentration of cholesterol in the blood. "The expression of mRNAs of FADS1 (Δ5-desaturase) and FADS2 (Δ6-desaturase) significantly decreased in the liver due to isolated hypercholesterolemia." (PMID 28750643, 2017).
large cell lymphomas (1 paper, 2024). "Both expression and metabolic activity of fatty acid desaturase 1 (FADS1) and FADS2 which synthesized AA from the precursor was not altered, suggesting that PUFA synthesis is unlikely to be involved in AA reduction in EBV-infected large cell lymphomas (LCLs)." (PMID 38719806, 2024).
latent infection (1 paper, 2025). "As EBV latent infection proceeds through a series of cell fate and activation transitions early after B cell infection before LCL outgrowth, we assessed the role of SCD1 and FADS2 in the early events in B cell transformation." (PMID 40403013, 2025).